MAP2K3 (mitogen-activated protein kinase kinase 3)
Diseases named in the same sentence as MAP2K3 in open-access papers (continued):
Sharing a sentence is not in itself a finding about the gene and the disease.
acute pancreatitis (3 papers, 2020 to 2023). An acute inflammatory process that leads to necrosis of the pancreatic parenchyma. "In acute pancreatitis, overexpression of RAB21 promotes the caerulein-induced MKK3 (mitogen-activated protein kinase kinase 3)-TRAF3 (TNF receptor-associated factor 3) association." (PMID 35163051, 2022).
atherosclerosis (3 papers, 2019 to 2021). A disease characterized by the build-up of fatty material and calcium deposition in the arterial wall resulting in partial or complete occlusion of the arterial lumen. "The protective effect of miR-21 in atherosclerosis was attributed to promoting macrophage survival and their phagocytic capacity alongside preservation of ABCG1 expression, a positive regulator of cholesterol efflux which is negatively regulated by the miR-21 target MAP2K3 (also known as MKK3)." (PMID 30389614, 2019).
lung carcinoma (3 papers, 2017 to 2024). "used a weighted gene co-expression network analysis screening method to identify four key genes that are shared with OSA and lung cancer, namely modulator of apoptosis 1 (MOAP1), chromobox 7 (CBX7), platelet-derived growth factor subunit B (PDGFB), and mitogen-activated protein kinase 3 (MAP2K3)." (PMID 38605948, 2024).
psoriasis (3 papers, 2020 to 2024). An autoimmune condition characterized by red, well-delineated plaques with silvery scales that are usually on the extensor surfaces and scalp. "For example, the gene Mitogen-Activated Protein Kinase Kinase 3 (MAP2K3) is known to increase expression in skin diseases such as psoriasis, acne vulgaris, and atopic dermatitis, and the regulation of MAP2K3 seems to be important for homeostasis." (PMID 38397178, 2024). "Psoriasis-associated plasma miRNAs target MAP kinases; it has been reported that miR-148a-3p targets MAPK1, MAP2K3, MAP3K4, and MAP4K3." (PMID 32411787, 2020).
pulmonary fibrosis (3 papers, 2024 to 2026). Chronic progressive interstitial lung disorder characterized by the replacement of the lung tissue by connective tissue, leading to progressive dyspnea, respiratory failure, or right heart failure. "Our data unveil a miR-214-3p-MAP2K3-p38 MAPK axis that constitutes a readily druggable target for rare-earth-element-induced pulmonary fibrosis." (PMID 41893497, 2026). "The present changes inhibited the expressions of mitogen-activated protein kinase kinase 3 and p38, which suppressed transforming growth factor-β, ultimately alleviating lung fibrosis." (PMID 40299673, 2025).
viral infection (3 papers, 2014 to 2023). "Next, we studied the possibility that MAP2K3 could be a modulation factor in cell stimulation by a synthetic double-stranded RNA poly(I:C), which is used experimentally to model viral infections in vivo and in vitro." (PMID 34299039, 2021).
gastric cancer (2 papers, 2020 to 2022). A primary or metastatic malignant neoplasm involving the stomach. "rs73302038 (chr17:g.21215682 G>A) in mitogen-activated protein kinase kinase 3 (MAP2K3), which was associated with resistance to VCR, showed the strongest association for the gastric cancer subgroup (P = 8.32 × 10−6, rs = 0.935)." (PMID 32986753, 2020).
heart failure (2 papers, 2011 to 2020). Inability of the heart to pump blood at an adequate rate to meet tissue metabolic requirements. "Also, some C/EBPβ target genes, for example, OSMR, MAP2K3 regulate the heart failure developmental progress." (PMID 32460775, 2020). "Some C/EBPβ target genes, for example, OSMR, MAP2K3 and CDKN1B also have been studied in heart failure developmental progress." (PMID 32460775, 2020).
liver cancer (2 papers, 2020 to 2025). An epithelial or non-epithelial malignant neoplasm that arises from the liver. "Our study shows that low expression of MAP2K3 can predict the occurrence of early liver cancer, and for patients with diagnosed liver cancer, high expression of MAP2K3 predicts a better prognosis." (PMID 40587753, 2025). "In the treatment of patients with this type of liver cancer, increasing MAP2K3 may be a more correct treatment." (PMID 40587753, 2025). "On the contrary, miR-21 can promote the proliferation of liver cancer, whose mechanism may be related to the direct targeted inhibition of miR-21 on MAP kinase-kinase 3 (MAP2K3)." (PMID 31966062, 2020). "Similarly, similar to MAP2K3, low expression of MAP2K4 can predict the occurrence of liver cancer, and high expression of MAP2K4 predicts better prognosis of patients." (PMID 40587753, 2025).
triple-negative breast carcinoma (2 papers, 2020 to 2023). An invasive breast carcinoma which is negative for expression of estrogen receptor (ER), progesterone receptor (PR), and human epidermal growth factor receptor 2 (HER2). "Likewise, comparatively high expression of the mitogen-activated protein kinase kinase 3, MKK3, which activates Myc transcription, is associated with an increased incidence of triple-negative breast cancer and a worse clinical outcome." (PMID 39086682, 2023). "Among those genes, the overexpression of mitogen-activated protein kinase kinase 3 (MKK3) has one of the most dramatic and race-specific negative impacts on the survival of African American patients, specifically with triple-negative breast cancer." (PMID 32873298, 2020).
ZIKV infection (2 papers, 2017 to 2018). "The inflammatory profile is partially different following ZIKV infection, which is mainly characterized by less inflammatory response and by the specific induction of several MAPK genes (MAP2K1, MAP2K3, MAP3K7, MAPK1, MAPK3)." (PMID 28873445, 2017).
cytomegalovirus infection (1 paper, 2021). A herpesvirus infection caused by Cytomegalovirus. "Late in the human cytomegalovirus infection period, MAP2K3 is increased and p38 MAPK is activated." (PMID 34299039, 2021).
esophageal squamous cell carcinoma (1 paper, 2021). Esophageal squamous cell carcinoma (ESCC) is a type of esophageal carcinoma (EC) that can affect any part of the esophagus, but is usually located in the upper or middle third. "The regulatory function of MAP2K3 was studied in esophageal squamous cell carcinoma (ESCC) progression." (PMID 33660414, 2021).
head and neck cancer (1 paper, 2025). A primary or metastatic malignant neoplasm affecting the head and neck. "MAP2K3 (MEK3, MKK3) p.Ala84Thr is seen in 24 samples within COSMIC, with the most common (10 samples) from head and neck cancers in respiratory and upper-digestive tract tumours and predicted to be activating." (PMID 41152984, 2025).
hepatitis A infection (1 paper, 2021). "The inhibition of MAP2K3 may also prevent HAV patients from developing a severe hepatitis A infection." (PMID 34299039, 2021). "The inhibition of MAP2K3 may prevent patients infected with HAV from developing severe hepatitis A." (PMID 34299039, 2021).
hepatitis C (1 paper, 2023). "Finally 6 genes (NCOR2, NR1H3, PPARA, IRF3, MAP2K3, and TLR6) were enriched in 3 immune-related pathways, including toll-like receptor signaling pathway, EB virus infection, and hepatitis C." (PMID 37845378, 2023).
HIV-1 infection (1 paper, 2020). The type species of lentivirus and the etiologic agent of acquired immunodeficiency syndrome (AIDS). "On the other hand, MAP2K3 engagement in the activation of p38-STAT1 pathway and activation of a subset of ISGs in antigen-presenting cells during HIV-1 infection was previously reported to facilitates expansion of the infection." (PMID 33679688, 2020).
lymph node metastasis (1 paper, 2022). "They showed that high expression of MAP2K3 was significantly correlated with CA125 level (p < 0.001), tumor size (p = 0.001), lymph node metastasis (p = 0.008), depth of myometrial invasion (p < 0.001), and FIGO stage (p < 0.001), indicating MKK3 as a poor prognostic biomarker." (PMID 35158751, 2022).
myocarditis (1 paper, 2019). Myocarditis is a condition that is characterized by inflammation of the heart muscle (myocardium). "Our previous study showed that miRNA-21 that potentially targets MAP2K3 is upregulated in the heart of mice with CVB3-induced myocarditis." (PMID 31585536, 2019).
overgrowth syndrome (1 paper, 2022). A group of syndromes caused by genetic birth defects that may lead to the development of malignancies. "In conclusion, customized panel-gene deep-sequencing enhanced the genetic diagnosis in patients with lateralized overgrowth syndrome, which furthermore identified the potentially causative new variants in MAP2K3 and TBC1D4." (PMID 36175890, 2022).
Stroke (1 paper, 2025). Sudden impairment of blood flow to a part of the brain due to occlusion or rupture of an artery to the brain. "Specifically, elevated miR-21 in the post-stroke brain inhibited the p38/MAPK signaling pathway by targeting MAP2K3 (MKK3), which led to reduced production of inflammatory cytokines, attenuated BBB permeability increase, and less vasogenic edema." (PMID 40981170, 2025).
vascular malformation (1 paper, 2022). A non-neoplastic disorder that is the result of defects of vascular morphogenesis. "The identified PIK3CA mutations have been previously reported in other patients with PROS, and the KRAS and TEK mutations in patients with vascular malformation, but the MAP2K3 and TBC1D4 mutations have not been previously reported." (PMID 36175890, 2022).
tumor (47 papers, 2011 to 2025). "MAP2K3 has been shown to enhance tumor progression, and the loss of MAP2K3 results in inhibition of cellular proliferation and increased response of tumor cells to chemotherapeutic drugs in vivo." (PMID 33660414, 2021). "We also used the TIDE algorithm and ESTIMATE algorithm to compare the relevant differences in the tumor immune microenvironment between the two MAP2K3 expression levels to quantify the association between MAP2K3 expression levels and potential immunotherapeutic effects." (PMID 38938778, 2024). "In our analysis, PRIM2 and MAP2K3 had monoallelic expression patterns in the majority of the cancer cell lines from 9 tumor categories." (PMID 40414875, 2025). "We scored the tumor immune microenvironment by scoring patients in different MAP2K3 expression groups, and as a result, the high MAP2K3 expression group was found to have a higher exclusion score." (PMID 38938778, 2024). "The analysis showed that all seven tumor immune cycle steps were scored higher in the high MAP2K3 expression group, which validates the important impact of the MAP2K3 gene on the tumor immune microenvironment (bottom part)." (PMID 38938778, 2024). "Since tumor progression and suppression are closely related to immunity, we investigated the differences in the immune microenvironment of tumors at different MAP2K3 expression levels." (PMID 38938778, 2024). "MAP2K3 promoted tumor progression by regulating tumor cell migration and invasion through the JNK signaling pathway." (PMID 37237254, 2023). "MAP2K3 was identified as an oncogene whose depletion reduces tumor growth and improves biological response to chemotherapy." (PMID 33660414, 2021). "In this study, we employed a clustered regularly interspaced short palindromic repeats/associated protein 9 (CRISPR/Cas9) kinome screened and identified MAP2K3 as an ESCC tumor suppressor gene." (PMID 33660414, 2021). "Mitogen‐activated protein kinase 3 (MAP2K3) has a contradictory role in tumor progression, and the function and expression patterns of MAP2K3 in ESCC remain to be determined." (PMID 33660414, 2021). "MAP2K3 (MKK3) specifically phosphorylates p38MAPK and activates tumor cell invasion and migration by a JNK-dependent pathway." (PMID 34455105, 2021). "Key signaling molecules exclusively affected by tumor-priming include MAP2K3, MARCKSL1, STAT5A, and TNFAIP3, which are specifically associated with NK cell cytotoxicity against tumor targets." (PMID 31242243, 2019). "Several studies have highlighted the critical role for MAP2K3 in tumor progression and targeted therapies." (PMID 30796273, 2019). "The ASE genes that was mostly recurrently observed in both tumor and normal samples had a high allele imbalance, such as AP3P1, BCLAF1, STED8, PRIM2, IL32, SEC22, and MAP2K3." (PMID 30538721, 2018). "For instance, mutations in the IGDCC4, ARHGEF18, MAP2K3 or AIF1L genes, which were observed in fractions exceeding 80% in the primary tumor ranged from 0 to 86% in the PDXs or secondary nodules." (PMID 26334103, 2015). "Indeed, considering only tumour-derived, confirmed somatic variants the counts are only 11 for PIM1 p.Ser97Asn and six for MAP2K3 p.Ala84Thr." (PMID 41152984, 2025). "TIMER database shows that MAP2K3 to 7 were significantly related to tumor purity." (PMID 40587753, 2025). "The results showed MAP2K3 to 7 were significantly correlated with tumor purity." (PMID 40587753, 2025). "The upregulation of MAP2K3 due to CTRP6 mutations may promote oncogenic transformation in primary cells, as MAP2K3 is known to support tumor cell survival and proliferation." (PMID 39979869, 2025).
tumor (continued). "By analyzing multiple clinical cohorts, we evaluated the impact of MAP2K3 expression levels on tumor immunotherapy and found a significant prognostic advantage in the high MAP2K3 expression group after anti-PD-1 immunotherapy, which is consistent with our predicted results." (PMID 38938778, 2024). "By analyzing the effect of MAP2K3 expression levels on chemokines in the tumor immune microenvironment, the results showed elevated expression of several chemokines in the MAP2K3 high expression group; such as CXCL10, CCR5, CCR10, CCL5, CCL7, CCR2, and CCL22 (upper part)." (PMID 38938778, 2024). "All of these results suggest that patients in the high MAP2K3-expressing group may derive more benefit from tumor immune checkpoint inhibitor therapy." (PMID 38938778, 2024). "In previous studies, MAP2K3 was identified as an oncogene, and reducing MAP2K3 expression could reduce the rate of tumor growth and improve the biological response to chemotherapy." (PMID 38938778, 2024). "Furthermore, the in vivo experiment supporting our in vitro results showed that tumor size and weight were significantly higher in MAP2K3‐KO tumors compared with controls, while STAT3 knockdown tumors had the smallest tumors." (PMID 33660414, 2021). "In addition, IHC was performed to detect the tumor growth in each group by Ki67 and MAP2K3 staining." (PMID 33660414, 2021). "However, in our study, we found that MAP2K3 inhibits cell proliferation and colony formation, indicating that MAP2K3 plays a tumor suppressor role in ESCC." (PMID 33660414, 2021). "Furthermore, MAP2K3 expression was significantly correlated with ESCC patient age and tumor differentiation, with well‐differentiated tumors displaying stronger MAP2K3 expression than poorly differentiated tumors." (PMID 33660414, 2021). "Clinical evidence shows that miR-21 acts as tumour suppressor by targeting MAP2K3 gene." (PMID 28122525, 2017). "Given that the TGF signaling pathway is crucial for controlling immune cell activity and tumor immune escape, we specifically focused on the relationship between TGF-β1, TGF-β2, TGF-β3, TGF-βR1, and this MAP2K3 expression level in the TGF signaling pathway." (PMID 38938778, 2024). "As indicative of an enriched immune tumor microenvironment, we found CXCR3, ZAP70 and PTPN22; whereas others, such as TIMP1 and MAP2K3, had higher correlation with endothelial markers indicative of a tumor-induced angiogenic process." (PMID 35875157, 2022). "The immunohistochemistry revealed that STAT3 and Ki‐67 expression was significantly higher in the MAP2K3‐KO group, while knockdown of STAT3 abolished this phenomenon, indicating that STAT3 knockdown diminished tumor activity induced by MAP2K3‐KO." (PMID 33660414, 2021). "TXNIP, TUSC2, PPFIBP2, GALNT10 and MAP2K3 demonstrated varying degrees of methylation on their promoter regions in normal mucosa, normal salivary rinses and HNSCC tumor samples respectively." (PMID 23403885, 2013). "In this study, we found that the mitogen-activated protein kinase-kinase 3 (MAP2K3) was markedly down-regulated in human HCC tissue, compared with adjacent non-tumor tissues for the first time." (PMID 24112539, 2013). "The expression of mitogen-activated protein kinase-kinase 3 (MAP2K3) in human HCC tumor tissues and adjacent non-tumor tissues was determined by immunohistochemistry staining (IHC) analysis." (PMID 24112539, 2013). "MiR-21-5p inhibited mitogen-activated protein kinase-kinase 3 (MAP 2 K3) to promote malignant proliferation of hepatocytes, and it may play an important role in tumor migration and infiltration regulation." (PMID 34001196, 2021). "By immunohistochemistry staining analysis, we found that mitogen-activated protein kinase-kinase 3 (MAP2K3) was strikingly repressed in the human HCC tumor tissues, in comparison with the adjacent non-tumor tissues in clinical settings." (PMID 24112539, 2013).
cancer (45 papers, 2009 to 2025). A tumor composed of atypical neoplastic, often pleomorphic cells that invade other tissues. "Our two new likely activating variants (in PIM1 and MAP2K3) have very low sample counts in current cancer datasets." (PMID 41152984, 2025). "We used the TIMER database to explore the expression of MAP2K3 in 33 human cancers and found that MAP2K3 was expressed in multiple tumors." (PMID 38938778, 2024). "In our study, based on an individual dataset of 33 tumors in the TCGA database, we analyzed the expression of MAP2K3 in different types of cancers." (PMID 38938778, 2024). "Although these findings supported that MAP2K3 plays a crucial role in cancer development, the expression and biological function of MAP2K3 in ESCC remains to be elucidated." (PMID 33660414, 2021). "Elevated protein expression of MAP2K3 was observed by IHC in normal epithelial (n = 140) when compared to case‐matched carcinoma in situ (CIS) (n = 12) and ESCC tissue(n = 140)." (PMID 33660414, 2021). "The MSigDB Cancer Neighborhood highlighted cancer-associated genes, TAL1, ANK1, SPTB, SPTA1, PRDX2, MAP2K3, etc.." (PMID 25522020, 2014). "In turn, statistically significant changes in MAP2K3 activity were reported in G3 cancer." (PMID 31795319, 2019). "However, the role of MAP2K3 in cancer has been challenged recently." (PMID 33660414, 2021). "We show that depletion of the MiDAC complex in a cancer cell line results in upregulation of the kinases MAP2K6 and MAP2K3." (PMID 41290615, 2025). "siRNAs specific for MAP2K3 were designed and transfected into SFE-treated cancer cells to determine the relationship between SFE and GADD45B." (PMID 32873775, 2020). "MAP2K3 is involved in the MAP kinase signaling pathways which has a critical role in cellular proliferation and differentiation in various contexts including cancer." (PMID 38831310, 2024). "MAP2K3 p.Ala84Thr has previously been classified as benign in a large screen of cancer somatic and germline genomes, likely as the kinase itself did not stand out as a major driver across the pan-cancer set." (PMID 41152984, 2025).